STAT1 (signal transducer and activator of transcription 1)
Diseases named in the same sentence as STAT1 in open-access papers (continued):
Sharing a sentence is not in itself a finding about the gene and the disease.
tumor (continued). "Given the known roles of STAT1 and TGFβ in modulating immune responses, the inhibition of these pathways by TCS9725 may influence tumor–immune interactions, potentially altering immune cell activation, infiltration, or suppression within the tumor microenvironment." (PMID 40699862, 2025). "Also, DHM inhibited MM tumor growth and EMT, and activated STAT1/RIG-I pathway in vivo." (PMID 39055888, 2024). "Mice with NLRP3 and caspase-1 deficiency subjected to AOM/DSS showed a dramatically increased tumor burden in the colon due to reduced IL-18 levels that altered the production and activation of the tumor suppressors IFN-γ and signal transducer and activator of transcription 1 (STAT1)." (PMID 39684769, 2024). "Although STAT1 expression is essential for effective antitumor T cell responses, tumour cell-specific expression may have negative consequences." (PMID 39328208, 2024). "Importantly, consistent with the results from Trp63-knockdown mouse model, STAT1-OE significantly decreased tumor growth and tumor weight relative to those in the control group without affecting the body weight of mice." (PMID 38509096, 2024). "In experiments with tumor-bearing mice, M.RGD@Cr-CTS-siYTHDF1 NPs, when exposed to laser irradiation, effectively killed tumor cells, disrupted the TME, delivered siYTHDF1 to TAMs, silenced the YTHDF1 gene, and shifted the STAT3-STAT1 equilibrium by reducing STAT3 and enhancing STAT1 expression." (PMID 38898486, 2024). "Strategies that disrupt the balance of the STAT1-IFITM3 negative feedback loop but do not eradicate this loop may be broadly applicable in clinical anti-tumor therapy by inducing Treg dysfunction." (PMID 38167862, 2024). "Hence, the different roles of STAT1 in tumorigenesis can be interpreted as either cell-autonomous or cell-nonautonomous mechanisms that predominate in tumor formation, dependent on the types of cancer involved." (PMID 38675812, 2024). "Downstream IFN-Ɣ pathway is inducing STAT1 activation achieving various biological functions such as IRF1 expression and tumor growth regulation, but STAT1 activation is also described for enhancing tumor progression through chronic inflammation responsible for controversial therapeutic implication." (PMID 37726776, 2023). "Tumor cells also underwent significant changes after mANK-101 treatment, including increased expression of proinflammatory chemokines CXCL9 and CXCL10, and upregulation of genes responsible for antigen processing and MHC I presentation, likely mediated by IFN-γ signaling through STAT1." (PMID 38063196, 2023). "Genes regulated by other members of the STAT family, such as STAT3, were not significantly enriched in DEGs, suggesting that miR-145 exerted its anti-tumor functions mainly through STAT1/2 transcriptional factors rather than through other members of the STAT family." (PMID 37727442, 2023). "In lung adenocarcinoma cells, OSM induces the inhibitory effect of the STAT1-dependent pathway and suppresses the activating effect of STAT3-dependent signaling, which, in combination, suppresses the expression of genes that regulate epithelial-mesenchymal transition and tumor metastasis." (PMID 38022653, 2023). "Paradoxically, STAT1 has also been shown to inhibit these phenotypes by enhancing transcription of CXCL9, CXCL10, and CXCL11, leading to longer overall survival and progression-free survival in patients, and reduction of ascites formation and tumor burden in ID8 OvCa murine models of disease." (PMID 37173951, 2023). "The average expression values of STAT1 (p < 0.001), STAT2 (p < 0.001), STAT3 (p < 0.001), STAT4 (p < 0.001), STAT5A (p < 0.001), STAT5B (p < 0.001), and STAT6 (p < 0.001) among immune subtypes C1-C6 in all tumor types were identified to have notable differences." (PMID 36968603, 2023). "Transfer of CAR4 but not CTRL4 T cells resulted in STAT1 translocation throughout the tumor." (PMID 37248395, 2023).
tumor (continued). "In comparison to STAT1, STAT4 expression was lower in all tumor progression stages and on a downward trend, which could be used to monitor tumor progression and formulate therapeutic options in clinical tumor therapy." (PMID 36968603, 2023). "We elucidated the molecular mechanism of how biomechanical force induces tumor progression, showing that it upregulates cancer stemness through integrin-cytoskeletal prestress-AIRE signals, while mediating the quiescence of stem like tumor cells through DDR/STAT1/P27 signaling." (PMID 37369642, 2023). "For example, tumor PD-L1 (tPD-L1) engagement with MIC PD-1 (m-PD-1) activates Src homology region 2-containing protein tyrosine phosphatase 2 (SHP2) to antagonize type 1 IFN and STAT1 pathway to repress Cxcl9 and impair CD8+T cell recruitment to lung metastases." (PMID 37380989, 2023). "Moreover, STAT1 was the only gene highly expressed in BRCA (p < 0.001, log2FC = 0.895) and also had escalated expression levels in many tumor types, such as CHOL (p < 0.001, log2FC = 2.327), COAD (p < 0.001, log2FC = 0.396), LIHC (p < 0.001, log2FC = 0.585) and STAD (p < 0.001, log2FC = 1.402)." (PMID 36968603, 2023). "Differential gene expression showed an enrichment of genes involved in T cell recruitment (CXCL9, CXLC10) and interferon-gamma activity (GBP1, STAT1) in the macrophage compartment of responding tumours, while non-responders were enriched in immunosuppressive markers (GPNMB, CCL18)." (PMID 38030622, 2023). "On the other hand, some upregulated genes, such as STAT1 and SMAD7, could have pro-tumor effects." (PMID 37834191, 2023). "M-MDSC from 4T1 tumor-bearing mice with induced tumor site infiltration has been reported to promote tumor metastasis by inducing nitric oxide synthase 2 (NOS2) production and activating STAT1 and STAT3 signaling pathways in tumor cells to induce EMT and CSCs phenotypes." (PMID 37465670, 2023). "Interestingly, STAT1 and STAT3 exhibited highly positive correlations in the tumor epithelium." (PMID 35267462, 2022). "Taken together, these findings indicate that PD-1/PD-L1 activity in immune cells is dependent on STAT1 expression by tumour cells during HNSCC but may be independent of STAT1 expression by immune cells." (PMID 35595823, 2022). "This suggests a non-cell autonomous anti-tumor role for STAT1." (PMID 35681772, 2022). "Both apigenin and luteolin (from 10 to 50 μM) inhibited STAT1 and STAT3 phosphorylation and decreased expression of STAT-dependent programmed death-ligand 1 (PD-L1), a major factor responsible for the suppression of the adaptive anti-tumor immune response in NSCLC and melanoma cell lines." (PMID 36555392, 2022). "Therefore, activated STAT1 and activated STAT3 signaling in the tumor cells was observed in a subsets of HCC patients and may indicate a specific HCC subgroup with high immune cell infiltration." (PMID 35267462, 2022). "This approach revealed that elevated levels of STAT1-mediated APP signalling downstream of a viral/dsRNA response in immune lineages correlated with improved RFS only in HiFi tumours; signalling that provides no prognostic value in the relatively good prognostic LoFi group." (PMID 35477539, 2022). "Our observation that STAT1 and STAT3 expression exhibit strong positive correlation in the tumor cells and the immune cell infiltrate suggest that both may similarly indicate the state of the tumor microenvironment." (PMID 35267462, 2022). "STAT1 signaling as and NF-κB were also shown as activated by polysaccharides isolated from the root of Ilex asprella (IAPS-2) or from Lachnum (a sort of mushroom) promoting secretion of anti-tumor cytokines by TAM and increasing animal survival rate in a sarcoma mouse model." (PMID 35163420, 2022).
tumor (continued). "FAK mediates the FAK/PI3K/AKT/PKB, FAK/Ras/MAPK, FAK/STAT1, FAK/GSK, FAK/GTPase, and growth factor (TGF-β) signaling pathways, which in turn are interconnected, ultimately affecting protein and gene expression involved in proliferation, invasion, and migration of tumor cells." (PMID 36193075, 2022). "Likewise, STAT1 and STAT6 activation is also found to be closely related to tumor progression." (PMID 35740527, 2022). "Notably, there is a negative correlation between METTL3/METTL14 and STAT1 in tumor tissues of 59 patients." (PMID 35693795, 2022). "Thus, a lack of STAT1 signaling induces a significant change in the colonic microenvironment that supports inflammation and tumor formation." (PMID 34299314, 2021). "IFN-γ is mainly produced by T and NK cells It can induce a positive feedback in the STAT1 pathway that triggers the expression and activation of STAT1 and other downstream genes, such as NLRC5, CIITA, and TAP1, and increases the immune response in the tumor microenvironment." (PMID 34220868, 2021). "Notably, Arg-1 and iNOS expression in the intestine was significantly diminished in STAT1-/- mice but not in WT mice during anti-IL-17 administration, which is consistent with the inhibition of tumor growth." (PMID 34299314, 2021). "Interestingly, STAT1 increases the expression of interleukin-18 binding protein (IL-18BP) and indoleamine 2,3-dioxygenase (IDO), an immunosuppressive enzyme that suppresses anti-tumor immunity." (PMID 33834023, 2021). "SOCS1, an IFN-γ/STAT1 inhibitor, is activated by HH signaling pathway itself to create a negative feedback loop and a downstream target of GLI1 and GLI2, which upregulates its transcriptional activity and subsequently relieve the IFN-γ/STAT1 form obstructing tumor growth." (PMID 33494284, 2021). "In real-world samples of patients with mCRC, we found that higher STAT1 expression in tumor cells was strongly indicative of a highly immunogenic microenvironment, with significantly higher expression levels of MHC class I and PD-L1, not only on tumor cells but also on non-tumor cells." (PMID 34758826, 2021). "In the early (day 20) and late (day 77) stages of tumor development, the accumulation of CD11b+Ly6ChiLy6G- monocytic cells among CD11b+ cells were increased in WT mice treated or not with anti-IL-17 blocking antibody, compared with STAT1-/- mice (p < 0.001)." (PMID 34299314, 2021). "The administration of the anti-IL-17 antibody significantly reduced pSTAT3 expression in STAT1-/- animals, suggesting that IL-17 may promote tumor growth in the absence of STAT1 through the activation of the STAT3 signaling pathway." (PMID 34299314, 2021). "Finally, in human NCI-H292 tumor epithelial cells, IFN-γ activates phospholipase C-γ (possibly via an upstream tyrosine kinase distinct from JAK1/JAK2) which induces the sequential activation of PKC-α c-Src and STAT1." (PMID 33668421, 2021). "In tumor lysates, STAT1 phosphorylation was not consistent with the presence of M2-polarized macrophages or IFNγ suggesting that the constitutive activation of STAT1 was not related to the JAK–STAT pathway." (PMID 32642677, 2020). "Collectively, our findings provide evidence that STAT1 isoforms are not functionally redundant in regulating NK cell activity and that the absence of STAT1α severely impairs, but does not abolish, NK cell-dependent tumor surveillance." (PMID 33042133, 2020). "In our PPI analysis, the majority of the genes in the most closely connected module were significantly upregulated in M1 macrophages, including STAT1, OAS1, OAS2 and DDX5; thus, developing small molecule agonists for these proteins may enhance anti-tumor immunity." (PMID 33323552, 2020). "M1 subtype macrophages differentiate through mainly JAK1/2, STAT1/2, 5, TLR4/NF-κB, P38 MAPK pathway activation, excrete inflammatory cytokines and chemokines, participate in a positive immune response; as such, they are able to kill tumor cells in tumor tissue and foreign pathogens." (PMID 32850623, 2020).
tumor (continued). "This STAT3/STAT1 balancing would (i) reprogram mesenchymal/CSC to a non-CSC state, making them more susceptible to chemotherapy and (ii) enhance anti-tumor immunity, thereby facilitating immune cell-mediated tumor cell killing." (PMID 31684144, 2019). "However, we observed no changes in the expression of STAT-1, ERK, or Src proteins in any of the tissues analyzed; therefore, we suggest that the proliferation of tumor cells occurs through a pathway independent of STAT-1." (PMID 31741709, 2019). "All these studies showed that STAT1 unlikely to promote tumor cell growth in human." (PMID 30847297, 2019). "In contrast, chronic exposure of cells to low IFNs under pathological conditions may steadily induce expression of ISGs that are controlled by u-STAT1, denoted as IFN-related DNA damage resistance signature (IRDS), which can promote tumor growth and metastasis." (PMID 30456450, 2019). "A novel non-canonical function of STAT1 at the immunological synapse of NK cells regulating tumor surveillance and cytotoxicity may account for that effect." (PMID 31781102, 2019). "Our data support the hypothesis that not all IL-1β signalling is involved in tumour promotion, as IL-1β is capable of stimulating caspase-11 expression, which can subsequently mediate STAT1 activation in IECs." (PMID 30538296, 2019). "This is exampled by the induction of STAT1 and STAT3 by IFN-γ, whereby T cell differentiation is skewed toward Th1 by STAT1 and Th17 by STAT3, and that tumor cell proliferation might be restricted by STAT1 yet enhanced by STAT3—differential effects largely mediated by SOCS protein associations." (PMID 31842362, 2019). "Additionally, miR-29 exhibits anti-tumor effects outside of angiogenesis, including cell cycle inhibition and apoptosis promotion, and appears to elicit synergistic effects with MYC inhibition and STAT1 activation." (PMID 31382461, 2019). "Interestingly, chronic IFN-γ exposure rendered tumor cells resistant to ICBs through epigenome/transcriptome changes driven by JAK/STAT1, which is independent of PD-L1 expression." (PMID 30135516, 2018). "Likewise, in EG7 lymphoma, B16, and inducible BrafV600EPTEN melanoma models exogenous IL-33 activated myeloid DCs within the tumor microenvironment increasing antigen cross-presentation and restoring anti-tumor T cell activity in a ST2, MyD88, and STAT1-dependent manner." (PMID 30483263, 2018). "We show that an elevated STAT1 transcriptional response is associated with a robust increase in GZMB (13-fold), CD8A (4.3-fold) and PD-L1 (2.6-fold) expression levels in STAT3Low tumours but not in STAT3High tumours (1.9-fold, 1.4-fold and 1.1-fold, respectively)." (PMID 28276425, 2017). "In addition to canonical NF-κB pathways, STAT1, STAT3, JUN, EGFR, and CEBPB were also on the top list, and these proteins may play crucial roles in tumour-induced DC signal transduction." (PMID 28350008, 2017). "The inflammatory milieu of the tumor microenvironment affects different intracellular master regulators of TAMs such as Signal Transducer and Activator of Transcription factors (STAT3 and STAT6 for M2, STAT1 for M1 polarization), the nuclear factor-κB (NF-κB), RORC1, and HIF-1." (PMID 28197019, 2017). "Therefore, the aim of the present study was to examine the relationship between total and phosphorylated STAT1 and STAT3 tumour cell expression, components of the tumour microenvironment and survival in a mature cohort of patients with invasive ductal breast cancer." (PMID 27769057, 2016). "Thus, our study provided first evidence that ARTD9 together with STAT1β may negatively regulate a tumor suppressor network, while ARTD9 may concomitantly positively regulate a STAT1- dependent and independent proto-oncogene network in HR-subtype DLBCL." (PMID 26654227, 2015).
tumor (continued). "Thus, the 129:Stat1-null local or systemic environment poorly supports the growth of transplanted primary tumor cells and suggests that the tumor suppressor action of STAT1 in the microenvironment/host is not functional or effective." (PMID 26075897, 2015). "We show that silvestrol induces direct anti-tumor activity against EBV-transformed lymphoblastoid cell lines (LCL), with growth inhibition, decreased expression of the EBV oncogene latent membrane protein-1, and inhibition of the downstream AKT, STAT1 and STAT3 signaling pathways." (PMID 25393910, 2015). "Whether STAT3-mediated upregulation of STAT1 and CRP actually supports or suppresses tumor growth is not clear to this point despite both STAT1 and CRP potentially having both pro- and anti-tumor activity." (PMID 24743777, 2014). "In our study, immunohistochemical analysis was able to distinguish the expression of STAT1 in the tumor epithelium and stroma, yet it was not possible to discern whether expression in one of these two compartments was prognostically more relevant." (PMID 24725474, 2014). "The role of STAT1 as a tumor suppressor is not without controversy." (PMID 25355139, 2014). "The tumor-suppressive role of STAT1 in the IFN pathway and the reported association between the lack of STAT1 and the IFN resistance raise the concern that ZOL may diminish IFN response in RCC patients." (PMID 23741352, 2013). "The density of CD8+ T cells and CD33+/p-STAT1+ cells was significantly correlated with patient vital status (p = 0.023, p < 0.001) and relapse occurrence (p = 0.005, p = 0.001); in addition, the high-density group of CD8+ T cells had a smaller tumor size (p = 0.005)." (PMID 23307253, 2013). "Since phosphorylation in Ser 727 is functionally distinct from and independent of that in Tyr 701, the inability of the S727A mutant to abrogate cell death suggests that tumor suppression mediated by STAT1 does not require S727-dependent target genes, like GBP-1." (PMID 22264274, 2012). "However, established tumors failed to progress after ovariectomy, indicating that the STAT1-/- ERα+/PR+ tumor cells require ovarian hormones not only for in vivo engraftment but also for maintenance of growth." (PMID 22264274, 2012). "Thus, the tumor suppressor action of STAT1 requires tyrosine phosphorylation, but not serine phosphorylation, of STAT1." (PMID 22264274, 2012). "Our findings thus indicate that the regulation of STAT1 expression is cell context-dependent and a STAT1 activation signature in whole-tumor biopsy might not reflect the biology of the entire tumor microenvironment." (PMID 22264274, 2012). "A new hairpin decoy oligonucleotide (hpdODN) carrying STAT3's DNA binding consensus sequence was designed following 3D analysis of protein/DNA interaction and shown to induce the death of STAT3-dependent tumor cells without interfering with STAT1, a key effector of cell death." (PMID 22423663, 2012). "Similarly to the IFNγ/STAT1 signaling, STAT3 and IL-10 can form a positively regulatory loop to promote tumor progression and metastasis through sustaining immunosuppressive environment in tumor tissue." (PMID 21931823, 2011). "Although the precise mechanism is required further investigation, tumor cell-induced STAT3 activation may largely be responsible for the suppression of IFNγ/STAT1 signaling and Th1 responses in mice treated with the TLR4/9 agonist complex after tumor cell inoculation." (PMID 21931823, 2011). "By losing STAT1 the cells may down-regulate MHCI and thus escape CTL-mediated tumor surveillance." (PMID 22185785, 2011). "Indeed, macrophages with silenced IL-1β or STAT1 or vitamin D3 treated macrophages, which failed to protect tumor cells from TRAIL-induced apoptosis, also failed to stabilize Snail in tumor cells." (PMID 20661477, 2010).